OGG1 (8-oxoguanine DNA glycosylase)
Diseases named in the same sentence as OGG1 in open-access papers (continued):
Sharing a sentence is not in itself a finding about the gene and the disease.
breast carcinoma (28 papers, 2006 to 2024). "Wang T., Wang H., Yang S., Guo H., Zhang B., Guo H., Wang L.,Zhu G., Zhang Y., Zhou H., Zhang X., Li H., Su H. Associationof APEX1 and OGG1 gene polymorphisms with breast cancer riskamong Han women in the Gansu Province of China." (PMID 39027127, 2024). "We estimated the relationship between APEX1 and OGG1 gene polymorphisms and breast cancer risk among 1430 Han women of Northwest China in this experiment using a tag SNP-based study." (PMID 29720094, 2018). "The current study aimed to estimate the association of APEX1 and OGG1 polymorphisms with the risk of breast cancer development." (PMID 29720094, 2018). "Present study is designed to observe the mutational spectrum of OGG1 and its association with different environmental, clinical, and histopathological parameter in breast cancer patients in Pakistani population." (PMID 26089588, 2015). "Second part of present study involved 925 subjects including 530 breast cancer patients and 395 cancer-free healthy individuals as control used for mutational analysis of OGG1 gene." (PMID 26089588, 2015). "In first part of this study association between OGG1 polymorphisms and breast cancer susceptibility was explored by meta-analysis." (PMID 26089588, 2015). "In first part of study a meta-analysis was performed to evaluate the association between OGG1 polymorphisms and cancer susceptibility especially as risk factor of breast cancer." (PMID 26089588, 2015). "Of all eligible studies, the majority of studies were on head and neck, lung, and colorectal cancers whereas only 6 studies evaluated the OGG1 polymorphism in breast cancer." (PMID 26089588, 2015). "In conclusion, we have observed a significant association of germ line mutations of OGG1 with breast cancer in Pakistani population in this study." (PMID 26089588, 2015). "In conclusion, a significant association was observed between OGG1 germ line mutations and breast cancer risk." (PMID 26089588, 2015). "Our results suggested that the OGG1 Ser326Cys polymorphism was significantly associated with increased breast cancer risk in Asian populations and postmenopausal patients." (PMID 24893568, 2014). "A decreased OGG1 enzyme expression level has been associated with an aggressive breast cancer phenotype." (PMID 23697596, 2013). "Previous studies of our group have associated polymorphisms on genes related to oxidative stress (rs3736729 on GCLC and rs207454 on XDH) and DNA damage repair (rs1052133 on OGG1) with a predisposition to develop breast cancer." (PMID 23443115, 2012). "Additionally, a significant association was observed between OGG1 germline mutations and breast cancer risk, which are considered promising targets for the diagnosis, treatment, and prevention of breast cancer." (PMID 36620083, 2022). "Based on genetic characteristics of individuals included in this study, results suggest that MTHFR CT and OGG1 Cys/Cys genotypes have a protective effect that may have an influence on breast cancer risk in a representative Northern Sardinian population." (PMID 32192442, 2020). "The present work aimed to investigate whether APEX1 and OGG1 gene polymorphisms (frequency ≥ 5%) exert any synergistic effects on breast cancer risk." (PMID 29720094, 2018). "Our study suggested that OGG1 Ser326Cys polymorphism might contribute to breast cancer risk, especially in Asian populations and postmenopausal patients." (PMID 24893568, 2014). "The present meta-analysis suggests that the OGG1 Ser326Cys polymorphism may be a risk factor for breast cancer in Asians and postmenopausal patients." (PMID 24893568, 2014). "Furthermore, the GG genotype frequency of OGG1-rs1052133 polymorphism revealed a nominal association with lower risk of breast cancer in the recessive model (GG vs. CC/CG, OR: 0.23, 95% CI: 0.05–1.11, p = 0.0465, with the trend confirmed in the codominant model for GG genotype (p = 0.05)." (PMID 32192442, 2020).
breast carcinoma (continued). "To test this, we decided to evaluate the glycosylase OGG1 as a potential candidate, by treating BRCA1 proficient and deficient breast cancer cells with PARPi olaparib and the OGG1 inhibitor TH5478." (PMID 35619904, 2022). "However, reduced OGG1 protein, and thus activity, has been observed in prostate cancer cells, and reduced OGG1 has also been associated with increased risk of head and neck squamous cell carcinoma and with an aggressive form of breast cancer observed utilizing patient tumor samples." (PMID 33282879, 2020). "Second part of present study is designed to screen all intronic and exonic regions of OGG1 gene in 925 individuals including 530 breast cancer patients and 395 controls using PCR-SSCP followed by sequencing." (PMID 26089588, 2015). "Initially a meta-analysis was performed involving previous studies and then the results were compared to obtain a clear picture about the role of OGG1 variations in breast cancer." (PMID 26089588, 2015). "We have found six polymorphisms in OGG1, GPX6, SOD3, TXN and XDH genes significantly associated with predisposition to breast cancer." (PMID 25416100, 2014). "To provide the most comprehensive assessment of the associations between OGG1 Ser326Cys and APEX1 Asp148Glu polymorphisms and breast cancer risk, we performed an updated meta-analysis of all available studies." (PMID 24893568, 2014). "Many epidemiological studies have been performed to evaluate the role of OGG1 Ser326Cys and APEX1 Asp148Glu polymorphisms on breast cancer risk; however, the results remained conflicting and contradictory." (PMID 24893568, 2014). "Many epidemiological studies have evaluated the association between polymorphisms in the two BER genes (OGG1 Ser326Cys and APE1 Asp148Glu) and breast cancer risk." (PMID 24893568, 2014). "Based on our search criteria, 24 studies relevant to the role of OGG1 Ser326Cys and APEX1 Asp148Glu polymorphisms on breast cancer susceptibility were identified." (PMID 24893568, 2014). "To provide the most comprehensive assessment of the association between OGG1 Ser326Cys and APEX1 Asp148Glu polymorphisms and breast cancer risk, we performed this meta-analysis of all available studies." (PMID 24893568, 2014). "In this study, we present evidence that antioxidants, Vit C- and BHA-mediated induction of NRF2 regulates OGG1 which is involved in the inhibition of E2-induced oxidative DNA damage and possibly breast carcinogenesis in the rat model of breast cancer." (PMID 23697596, 2013). "We investigated the effect of E2 treatment on the mRNA expression of OGG1 during early exposure time to estrogen (7 days) and during neoplastic (240 days) stages of breast cancer development in female ACI rats." (PMID 23697596, 2013). "The expression of OGG1 was suppressed in mammary tissues and in mammary tumors of rats treated with E2." (PMID 23697596, 2013). "Previous data from our group relate the polymorphisms rs1052133 on the OGG1 gene, rs207454 on the XDH gene and rs3736729 on the GCLC gene to susceptibility to breast cancer." (PMID 23443115, 2012). "Interestingly, it has very recently been described that BRCA1-deficient breast cancer cells are sensitised to TH5487 demonstrating a new synthetic lethal partnership between HR deficiency and OGG1 inhibition." (PMID 38368415, 2024). "Furthermore, the OGG1 and XRCC1 rs25487 polymorphisms were nominally associated with PgR, Her2 status and with sporadic breast cancer, respectively." (PMID 32192442, 2020). "A total of 518 patients with histopathologically confirmed breast cancer and 921 region- and age-matched cancer-free controls were genotyped for the APEX1 polymorphisms rs3136817 and rs1130409 and the OGG1 polymorphisms rs1052133 and rs2072668 using a QuantStudioTM 12 K Flex Real-Time PCR System." (PMID 29720094, 2018).
breast carcinoma (continued). "These molecular and epidemiological findings provide evidence that OGG1, a DNA repairing gene, could prove to be a good candidate of better diagnosis, treatment, and prevention of breast cancer." (PMID 26089588, 2015). "The gene-gene interactions demonstrated a significant four-variant interaction among rs406113 (GPX6), rs974334 (GPX6), rs105213 (OGG1) and rs2284659 (SOD3) (p-value = 0.0008) with high-risk genotype combination showing increased risk for breast cancer (OR = 1.75 [95% CI; 1.26-2.44])." (PMID 25416100, 2014). "We have demonstrated that long-term continuous E2 exposure (240 days) significantly suppressed the expression of OGG1, an enzyme involved in oxidative DNA damage repair and thus may lead to increased DNA damage in mammary tumors and mammary tissues." (PMID 23697596, 2013). "The decrease in OGG1 mRNA expression in mammary tissues was evident as early as 7 days of E2 treatment and remained significantly decreased in both mammary tissues and E2-induced mammary tumors after 240 days of E2-treatment (neoplastic stage)." (PMID 23697596, 2013). "In parallel with decrease in NRF2 protein expression, a significant decrease in OGG1 protein expression in E2-treated mammary tissues and in mammary tumors, and an increase in OGG1 protein expression in mammary tissues of animals treated with Vit C- and BHA was demonstrated." (PMID 23697596, 2013). "Decreased mRNA and protein expression of NRF2 and OGG1 in E2-treated mammary tissues and in E2-induced mammary tumors after 240 days of E2 treatment and corresponding increased mRNA and protein expression of these genes after Vit C or BHA treatment suggest NRF2-mediated regulation of OGG1." (PMID 23697596, 2013). "Therefore in this study, we examined whether the regulation of OGG1 in E2-induced breast cancer is mediated through transcription factor NRF2." (PMID 23697596, 2013). "To examine whether antioxidants Vit C and BHA also protect against E2-mediated suppression of OGG1, we performed real-time PCR and western blot analysis with mammary tissues and mammary tumor samples from rats treated with E2, Vit C or BHA in presence or absence of E2 for 240 days." (PMID 23697596, 2013). "A four-way interaction found that between rs406113 on the GPX6 gene, rs974334 on the GPX6 gene, rs1052133 on the OGG1 gene and rs2284659 on the SOD3 gene predicts breast cancer with a testing balance accuracy of 0.5267." (PMID 25416100, 2014). "The exact relationship between genetic polymorphisms of OGG1 Ser326Cys and APEX1 Asp148Glu and breast cancer susceptibility has not been entirely established." (PMID 24893568, 2014). "To date, many epidemiological studies have been performed to evaluate the association between OGG1 Ser326Cys and APEX1 Asp148Glu polymorphisms and breast cancer risk, but the results remain conflicting rather than conclusive." (PMID 24893568, 2014). "mRNA and protein levels of a DNA repair enzyme 8-Oxoguanine DNA glycosylase (OGG1) and a transcription factor NRF2 were quantified in the mammary and mammary tumor tissues of rats after treatment with E2 and compared with that of rats treated with antioxidants either alone or in combination with E2." (PMID 23697596, 2013). "Significantly decreased expression of OGG1 at both mRNA and protein levels after long term E2 treatment and reversal of this suppression by Vit C and BHA in our study clearly indicates an important role of OGG1 in antioxidant-mediated protection against oxidative DNA damage as well as breast cancer." (PMID 23697596, 2013).
Obesity (28 papers, 2012 to 2025). Accumulation of substantial excess body fat. "In contrast, among the genes interacting with key adipogenic factors, LPXN, TNC, THBS1, and OGG1 have been directly associated with obesity and fat accumulation." (PMID 40130165, 2025). "OGG1 deficiency results in an increased susceptibility to high fat diet (HFD)-induced obesity, fatty liver, metabolic dysfunction, and glucose intolerance in mice, suggesting a crucial role of OGG1 in glucose metabolism." (PMID 39596235, 2024). "In conclusion, our findings uncovered a critical role of OGG1 deficiency in promoting HFD-induced hepatic insulin resistance which led to whole-body insulin resistance in a diet-induced obesity mouse model." (PMID 39596235, 2024). "Previous studies showed that OGG1 deficiency results in an increased susceptibility to high-fat diet (HFD)-induced obesity and metabolic dysfunction in mice, suggesting a crucial role of OGG1 in metabolism." (PMID 39596235, 2024). "In our study, we found that OGG1 was upregulated in adipose tissue from participants with obesity in comparison with healthy participants and associated with insulin levels, indicating a role in obesity and insulin sensitivity in the human context." (PMID 36982562, 2023). "They first found that Ogg1-/- mice were more susceptible to obesity and metabolic dysfunction relative to control mice." (PMID 36354755, 2022). "OGG1 deficiency has been associated with the development of insulin resistance and obesity in mice with increasing age (12-15 months)." (PMID 35391931, 2022). "Global deletion of either of two different glycosylases with varying substrate specificities, Nei-like endonuclease 1 (NEIL1) or 8-oxoguanine DNA glycosylase-1 (OGG1), both predispose mice to diet-induced obesity (DIO)." (PMID 34604220, 2021). "In contrast to obesity and glucose intolerance resulting from OGG1 deficiency, we recently reported that constitutive overexpression of mitochondrially-targeted human OGG1 significantly protected mice from high-fat diet induced obesity and adiposity." (PMID 33503804, 2021). "Loss of DNA repair of oxidized base lesions due to deficiencies in DNA glycosylase NEIL1, 8-oxoguanine DNA glycosylase OGG1 or DNA polymerase η result in obesity, hyperinsulinemia and hyperglycemia." (PMID 33493548, 2021). "These phenotypes in isolated preadipocytes and 3T3 cells correspond with obesity predisposition or resistance in Ogg1–/– and Ogg1Tg animals, respectively." (PMID 34604220, 2021). "Our laboratory has shown that OGG1 deficiency renders mice susceptible to metabolic pathologies including obesity, insulin resistance, and ectopic lipid accumulation." (PMID 31935236, 2020). "In a similar, better-characterized paradigm, mice deficient for the BER glycosylase OGG1 are prone to obesity and insulin resistance, due to a specific reduction in fatty acid oxidation." (PMID 30700008, 2019). "Our prior reports of obesity-proneness in OGG1-deficient animals, combined with these data, cement a role for OGG1 in the regulation of metabolic homeostasis." (PMID 30291284, 2018). "Concomitantly, several groups have reported a correlation between polymorphisms in the OGG1 gene and incidence of obesity and type II diabetes in human cohorts." (PMID 28727777, 2017). "As well, the loss or inhibition of OGG1 and subsequent accumulation of 8-oxodG in the genome are associated with cancer, neurodegenerative diseases, metabolic diseases, obesity, and autism." (PMID 27032448, 2016). "Collectively, these data indicate that OGG1 deficiency alters cellular substrate metabolism, favoring a fat sparing phenotype, that results in increased susceptibility to obesity and related pathologies in Ogg1−/− mice." (PMID 23284747, 2012). "In general, our results showed evidence that OGG1 can regulate CRC risk through obesity and may act as a biomarker for CRC." (PMID 36982562, 2023).
Obesity (continued). "In addition, we intend to evaluate the Ser326Cys OGG1 polymorphism to understand its association with obesity and cancer." (PMID 36982562, 2023). "Ogg1−/− mice were found to resist endogenous toxicity-induced organ dysfunction, neutrophil infiltration, and oxidative stress, but at the same time, Ogg1−/− mice fed a high-fat diet exhibited higher fasting plasma insulin levels and increased susceptibility to obesity and diabetes." (PMID 37372030, 2023). "Given our prior observations of increased propensity to obesity in OGG1-deficient mice, we sought to determine if OGG1 status, in the context of a regular low-fat diet or a hypercaloric diet, impacts intestinal microbial composition and whether any observed changes are associated with disease risk." (PMID 31935236, 2020). "Additionally, it is well-established that the accumulation of 8-oxodG in the genome caused by inhibition of OGG1 is a key event in the pathogenesis of several human pathologies, including cancer, neurodegeneration, Parkinson's disease, and obesity and metabolic dysfunction." (PMID 25423485, 2014). "Results of long-term HFD feeding demonstrated that targeting of hOGG1 into mitochondria of Ogg1-KO mice reduced HFD-induced obesity." (PMID 39596235, 2024). "In vivo correction of Ogg1-initiated mtDNA repair by transgenic expression of a mitochondria-targeted human OGG1 resulted in resistance to obesity and metabolic syndrome." (PMID 38779538, 2024). "In our study, we observed an upregulation of OGG1, likely a protective, albeit insufficient, response aimed at mitigating obesity-induced oxidative DNA damage." (PMID 39043652, 2024). "In the present study, we conducted a complete analysis of the transcriptional and epigenetic profiles of OGG1 in participants with obesity, as well as in patients with CRC." (PMID 36982562, 2023). "Specifically, transgenic mice overexpressing human OGG1 in the mitochondria had significant protection against obesity and adipose tissue inflammation when exposed to a high-fat diet, demonstrating a critical role in energy homeostasis." (PMID 36982562, 2023). "Enhanced protection against oxidative mitochondrial DNA damage by mitochondrially targeted overexpressed OGG1 induces a similarly favourable metabolic phenotype with improved mitochondrial energetics and a reduced body weight in a mouse model of obesity." (PMID 35670027, 2022). "Using preadipocytes from transgenic mice targeting OGG1 to mitochondria (Ogg1Tg mice), they found a protective role of OGG1 against diet-induced obesity, IR, and adipose tissue inflammation." (PMID 36354755, 2022). "We demonstrate for the first time that enhanced expression of the human OGG1 gene confers protection against genetically-induced obesity." (PMID 34604220, 2021). "An intriguing discovery of these studies is that of obesity resistance being determined by the maternal OGG1 genotype." (PMID 34604220, 2021). "Recent studies have demonstrated that poly(ADP-ribosyl)ation (PARylation) of cellular proteins inhibits adipogenesis, and a whole-body knockout model of PARP1 was shown to develop obesity and increased adiposity, similar to the Ogg1−/− mouse." (PMID 33503804, 2021). "We also report for the first time that OGG1-mediated obesity resistance in both the Ay/a model and DIO model requires maternal transmission of the hOGG1 transgene." (PMID 34604220, 2021). "Specifically, mice with a global deletion of the Ogg1 gene (Ogg1−/−) are prone to both age-induced and diet-induced obesity and adiposity." (PMID 33503804, 2021). "Further, they also uncover a critical role for maternal OGG1 genotype in determining obesity resistance both in the context of genetically-induced as well as DIO." (PMID 34604220, 2021). "We have previously reported that the DNA repair enzyme OGG1 plays an unexpected and novel role in the development of obesity and adiposity." (PMID 33503804, 2021).